SLFN11 (schlafen family member 11)
Diseases named in the same sentence as SLFN11 in open-access papers (continued):
Sharing a sentence is not in itself a finding about the gene and the disease.
prostate carcinoma (16 papers, 2017 to 2025). A carcinoma that arises from epithelial cells of the prostate gland. "SLFN11 is overexpressed in a significant proportion of advanced prostate cancers, including approximately 45% of metastatic castration-resistant prostate cancer (mCRPC) and 25% of primary prostate cancer." (PMID 40766331, 2025). "For example, Murai and colleagues showed that DNA replication stress induces the SLFN11-dependent upregulation of c-Jun and c-Fos expression in leukemia and prostate cancer cell lines." (PMID 37599787, 2023). "It is important to validate these findings in other prominent cancer cell types where the correlation between SLFN11 expression and chemosensitivity has been established, such as lung, colon or prostate cancer." (PMID 38001424, 2023). "Circulating tumor cells (CTCs) from metastatic CRPC patients show SLFN11 gene methylation, suggesting the need for SLFN11 silencing in prostatic cancer cells to gain metastatic ability." (PMID 34571887, 2021). "The lowest median SLFN11 expressors were colon and prostate cancers, the highest were kidney and head and neck cancers, and these findings corroborated with prevalence studies in patient-derived-xenograft models and clinical samples." (PMID 34663950, 2021). "High SLFN11 expression in prostate cancer patient-derived xenografts also increases their sensitivity to LMP400." (PMID 34571887, 2021). "We then focused on OV7 cells that express SLFN11 at similar levels compared with DU145 prostate cancer cells." (PMID 34549724, 2021). "The positive regulation of SLFN11 expression by CD47 extends to prostate cancer cells, and correlative data in human tumors extends this relationship to a subset of human cancers." (PMID 31632920, 2019). "We further analyzed TCGA prostate cancer data to evaluate a potential role of CD47 in these two mechanisms for regulating SLFN11 transcription." (PMID 31632920, 2019). "Consistent with the drug screening data, ChIP data identified CD47-dependent regulation of histone modification in the SLFN11 promoter in prostate cancer cells." (PMID 31632920, 2019). "The SLFN11 promoter contains several ETS binding sites and functions as an ETS factor response gene, with ETS transcription factors FLI1 and ETS1 having proposed roles in regulating SLFN11 expression in colon, breast, and prostate cancers." (PMID 28212573, 2017). "In addition, SLFN11 has shown encouraging potential as a predictive biomarker for response in ovarian and prostate cancer." (PMID 38255825, 2024). "Disruption of CD47 in PC3 prostate cancer cells similarly decreased SLFN11 expression and was associated with a CD47-dependent decrease in acetylation and increased methylation of histone H3 in the SLFN11 promoter region." (PMID 33925464, 2021). "Moreover, knockdown of CD47 in prostate cancer PC3 cells reduces both SLFN11 mRNA and protein levels, indicating SLFN11 is a target of CD47 in prostate cancer cells." (PMID 34571887, 2021). "SLFN11 expression increases the sensitivity of prostate cancer cells to platinum-based drugs in vitro, and knockout of SLFN11 in human prostate cancer organoids increases the resistance to Cisplatin and Olaparib (Poly (ADP-ribose) polymerase inhibitors, PARPi) in prostatic organoids." (PMID 34571887, 2021). "By performing transcriptomic and single-cell analyses, we found that gemcitabine treatment in prostate cancer cells induced the expression of immune-related pathways in SLFN11-proficient cancer cells, which is in line with recent findings made with other compounds inducing replication stress." (PMID 34549724, 2021). "Also, SLFN11-overexpressing prostate cancer patients show less serum prostatic specific antigen (PSA) than patients with low SLFN11 tumors." (PMID 34571887, 2021). "We chose the PC3 line to examine whether CD47 also regulates SLFN11 expression and sensitivity to genotoxic stress in prostate cancer cells." (PMID 31632920, 2019).
prostate carcinoma (continued). "Disruption of CD47 in PC3 prostate cancer cells similarly decreased schlafen-11 expression and was associated with a CD47-dependent decrease in acetylation and increased methylation of histone H3 in the SLFN11 promoter region." (PMID 31632920, 2019). "SLFN11 was identified in 2012 as a prognostic marker for response to DNA damaging agents in-silico) and was subsequently found to affect treatment response in brain and prostate cancer cells through its role in replication checkpoint maintenance and homologous recombination repair." (PMID 38001424, 2023). "Moreover, CD47 regulates SLFN11 expression in prostate cancer through promotor methylation." (PMID 34571887, 2021). "To assess whether SLFN11 influences IFN-γ- and DDA-induced cell death in a parallel manner in different cell systems, we generated SLFN11 KD variants of the prostate cancer cell line DU145 and the melanoma cell line WM2446, chosen because of their high levels of SLFN11 expression." (PMID 30753225, 2019). "Of the 7 prostate cancer cell lines in the CCLE, LNCAP and 22RV1 were high SLFN11 expressers, PC3 was moderate, and the remaining 4 were low expressers." (PMID 31632920, 2019). "Similar to what has been observed in lung cancer, CD47 positively correlates with SLFN11 expression in prostate carcinoma but not in normal prostate tissue." (PMID 34571887, 2021). "A weaker negative correlation between CD47 mRNA expression and SLFN11 promoter methylation (p = 4.6 × 10−19) suggested that the regulation of SLFN11 expression in human prostate cancers by CD47 is mediated in part by this mechanism." (PMID 31632920, 2019). "We recently reported that lack of SLFN11 expression induces proteotoxic stress and increases the sensitivity of cancer cells to TAK-243 in isogenic leukemia and prostate cancer cell line models." (PMID 38451783, 2024). "Patients with SLFN11-positive castration-resistant prostate cancer had improved radiographical PFS and prostate-specific antigen (PSA) tumor marker responses compared with patients without SLFN11 overexpression." (PMID 38255825, 2024). "Unlike the nuclear-localized SLFN5 and SLFN11, the intermediate family SLFN12, which lacks nuclear import signal and localizes to the cytoplasm, also has a differentiation effect in prostate cancer cells." (PMID 34571887, 2021). "Further analysis of the TCGA data for prostate cancers showed a positive correlation between CD47 and SLFN11 mRNA expression in the tumors but not in normal prostate tissues." (PMID 31632920, 2019).
Ewing sarcoma (15 papers, 2016 to 2026). A small round cell tumor that lacks morphologic, immunohistochemical, and electron microscopic evidence of neuroectodermal differentiation. "The induction of apoptosis caused by RNR inhibitors in Ewing sarcoma cells is due, in part, to high levels of SLFN11." (PMID 27557498, 2016). "Since SLFN11 is known to sensitize cancer cells to a number of drugs that cause DNA-damage, including DNA synthesis inhibitors, we tested the hypothesis that the sensitivity of Ewing sarcoma cells to RNR inhibitors may be caused by elevated levels of SLFN11." (PMID 27557498, 2016). "Ewing sarcoma (EWS) is a highly aggressive pediatric malignancy characterized by elevated expression of SLFN11, which impairs DNA repair by binding to and functionally inhibiting DNA repair complexes, thereby enhancing susceptibility to genotoxic therapies." (PMID 41620417, 2026). "SLFN11 is a key molecule in Ewing sarcoma that is directly regulated by the oncogenic driver EWS-FLI1." (PMID 40766331, 2025). "In Ewing sarcoma, SLFN11 is transcriptionally activated by the EWS-FLI1 oncogene and is required for sensitivity to PARP and topoisomerase I inhibitors." (PMID 40766331, 2025). "In comparison with the Ewing sarcoma cell lines, EWS protein was strongly expressed in all cell lines, while pAKT, PARP, and SLFN11 levels were lower in the PF1095 cells than in the two Ewing sarcoma S cell lines." (PMID 40134582, 2025). "We found that SLFN11 is expressed in the PF1095 cells but at a much lower level than in the two Ewing sarcoma cell lines." (PMID 40134582, 2025). "SLFN11 expression is a known predictor of sensitivity to DNA-damaging agents and it is usually abundantly present in Ewing sarcoma cells." (PMID 40134582, 2025). "In Ewing sarcoma (ES), SLFN11 was shown to be a direct transcriptional target of the core oncogenic driver EWS-FLI1, and its expression is positively regulated by EWS-FLI1 through promoter binding." (PMID 40766331, 2025). "Upregulation of AP-1 in Ewing sarcoma cells is dependent on SLFN11, which is a direct transcriptional target of the EWS-FLI1 oncoprotein and highly expressed in Ewing sarcoma tumors." (PMID 37599787, 2023). "We also identified that upregulation of these AP-1 transcription factors in Ewing sarcoma cells is dependent on SLFN11." (PMID 37599787, 2023). "We also identified that the upregulation of AP-1 is mediated, in part, by SLFN11, which is a replication stress response protein that is expressed at high levels in Ewing sarcoma." (PMID 37599787, 2023). "Supporting this notion are data from pediatric sarcomas including Ewing sarcoma, where SLFN11 is highly expressed." (PMID 36382088, 2022). "The cancers with consistently high SLFN11 expression are Ewing’s sarcoma and hematological malignancies." (PMID 34572827, 2021). "Several preclinical studies provided evidence for the role of SLFN11 in cytotoxic effects of PARPi and chemotherapy in for instance Ewing sarcoma and lung cancer." (PMID 34085099, 2021). "We also used a CRISPR/Cas9 gene knockout approach to investigate the role of Schlafen 11 (SLFN11), a restriction factor for DNA replication stress that is overexpressed in Ewing sarcoma tumors, in mediating the sensitivity of Ewing sarcoma cells to the drug." (PMID 33256675, 2020). "We also found that the sensitivity of Ewing sarcoma cells to eltrombopag is mediated, in part, by SLFN11, which regulates the cellular response to DNA replication stress." (PMID 33256675, 2020). "Overall, these results demonstrate that the high level of SLFN11 expressed in Ewing sarcoma cells mediates, in part, the enhanced sensitivity to eltrombopag." (PMID 33256675, 2020). "SLFN11 is overexpressed in Ewing sarcoma tumors and is known to sensitize cells to a range of drugs that cause DNA replication stress, including iron chelators." (PMID 33256675, 2020). "In other cancers, including Ewing sarcoma, SLFN11 has been described as an ETS transcription factor response gene." (PMID 28212573, 2017).
Ewing sarcoma (continued). "Because, Ewing's sarcoma initially responds to DNA damaging agents, for which cell killing depends on SLFN11, it will be important to determine the SLFN11 status of tumors in patients at relapse." (PMID 27708213, 2016). "We also identified that the elevated level of SLFN11 in Ewing sarcoma cells is responsible, in part, for the sensitivity of this sarcoma toward RNR inhibitors." (PMID 27557498, 2016). "In additional work, we discovered that high levels of SLFN11, a protein that sensitizes cells to drugs that cause DNA damage, is partially responsible for the toxicity of the RNR inhibitors toward Ewing sarcoma." (PMID 27557498, 2016). "The importance of SLFN11 for drug sensitivity has recently been extended to Ewing's sarcomas, and to patient responses in ovarian, non-small cell lung and colorectal cancers." (PMID 27708213, 2016). "In addition, Tang and colleagues showed that patients with Ewing sarcoma with higher SLFN11 expression exhibited better prognosis than those with lower SLFN11 expression." (PMID 37599787, 2023). "Also, SLFN11 is highly expressed in some cancers, such as Ewing sarcoma, pediatric sarcomas, mesothelioma, and renal cell carcinoma, while its expression is low in other types of cancer such as tumors of the ovary and pancreas." (PMID 36382088, 2022). "In addition, we identified that the overexpression of SLFN11 in Ewing sarcoma tumors mediates sensitivity to eltrombopag, which provides an explanation for some of the specificity of eltrombopag for Ewing sarcoma tumors in the screen." (PMID 33256675, 2020). "Consequently, we used CRISPR/Cas9 to knockout SLFN11 in two Ewing sarcoma cell lines, A673 and TC71." (PMID 33256675, 2020). "The SLFN11 data, in addition to providing a mechanistic explanation for the sensitivity of Ewing sarcoma cells to RNR inhibitors, also suggest that expression of this protein could function as a biomarker to predict drug response." (PMID 27557498, 2016). "Additionally, knockdown of SLFN11 also partially rescued Ewing sarcoma cells from the effects of ciclopirox on cell viability." (PMID 27557498, 2016). "We showed above that SLFN11 is expressed in PF1095 cells, although in lesser amounts than in the Ewing sarcoma cell lines." (PMID 40134582, 2025). "Cancer cell panel screening identified Ewing sarcoma (EWS) cells as sensitive to MSC778, which is driven by the expression of SLFN11." (PMID 41359388, 2025). "Schlafen family member 11 (SLFN11) is a transcriptional target of EWS-FLI1 and sensitizes Ewing sarcoma cells, as well as other cancer types, to a variety of DNA-damaging agents, including gemcitabine and additional RNR inhibitors." (PMID 37599787, 2023). "In Ewing sarcoma, the E26 transformation-specific (ETS) transcription factor (EWS-FLI1) is reported to drive SLFN11 to initiate a drug response." (PMID 32292519, 2020). "To determine the causal involvement of SLFN11 for PARPI sensitivity, we generated SLFN11-deleted (SLFN11-del) isogenic cell lines from four cell lines with high SLFN11 (prostate DU145, leukemia CCRF-CEM and MOLT4, and Ewing's sarcoma EW8) using CRISPR/Cas9." (PMID 27708213, 2016). "This has proven to be the case with PARP inhibition (PARPi) which displays synergistic activity in combination with ATRi in BRCA-mutant ovarian, SLFN11-negative prostate, leukemia, and Ewing’s sarcoma cell lines as well as in HR-proficient cell lines." (PMID 30057890, 2018). "Additionally, we discovered that the sensitivity of Ewing sarcoma cells to inhibition or suppression of RNR is mediated, in part, by high levels of SLFN11, a protein that sensitizes cells to DNA damage." (PMID 27557498, 2016). "In addition, our findings provide a link between the marked sensitivity of Ewing's sarcoma (EWS) cells to olaparib and the high SLFN11 expression in EWS cells." (PMID 27708213, 2016).
Ewing sarcoma (continued). "To test whether SLFN11 expression modulates the sensitivity of Ewing sarcoma cells to RRM2 knockdown we used siRNA to knockdown both SLFN11 and RRM2 in Ewing sarcoma cells." (PMID 27557498, 2016). "To determine whether SLFN11 directly affected the cytotoxic property of TAS1553, we examined the effect of SLFN11 knockdown using siRNA on the cytotoxicity of TAS1553 in an Ewing sarcoma cell line A673 (which had the highest SLFN11 expression among the 22 cell lines)." (PMID 35681099, 2022). "Additionally, we tested two Ewing's sarcoma cell lines, EW8 and A673 with high SLFN11 transcripts." (PMID 27708213, 2016).
ovarian carcinoma (15 papers, 2015 to 2025). A malignant neoplasm originating from the surface ovarian epithelium. "High expression (mRNA expression above the median) of SLFN11 is significantly associated with longer overall survival (OS) and better efficacy of platinum-based drugs in ovarian cancer patients receiving cisplatin chemotherapy." (PMID 40766331, 2025). "Low expression of SLFN11 has been associated with resistance to chemotherapy in ovarian cancer other cancers due to its role in the DNA damage response." (PMID 32698852, 2020). "Similarly, in a dataset of 110 ovarian cancer patients who received cisplatin chemotherapy, high SLFN11 expression showed a trend associated with longer OS (p = 0.053)." (PMID 40766331, 2025). "The preferential response to PARP inhibitors (PARPis) in BRCA-deficient and Schlafen 11 (SLFN11)-expressing ovarian cancers has been documented, yet the underlying molecular mechanisms remain unclear." (PMID 38961202, 2024). "Therefore, our findings provide novel mechanistic insights into potential favorable responses to olaparib in ovarian cancers characterized by high SLFN11 expression and BRCA-inactivating mutations." (PMID 38961202, 2024). "SLFN11 also confers hypersensitivity to PARPis in pre-clinical models, and a recent clinical study analyzing the effects of SLFN11 on olaparib sensitivity in patients with ovarian cancer showed that high SLFN11 expression is associated with improved clinical outcomes." (PMID 38961202, 2024). "Finally, in an ovarian cancer dataset of 110 patients, all of whom received cisplatin-based chemotherapy, high SLFN11 expression was associated with longer OS (HR = 1.79, p = 0.05)." (PMID 31682620, 2019). "SLFN11, known for inducing irreversible replication block, is emerging as a predictive biomarker in various cancer types, including ovarian cancer." (PMID 40069561, 2025). "SLFN11 is a powerful prognostic and predictive biomarker in ovarian cancer (especially high-grade serous ovarian cancer, HGSOC)." (PMID 40766331, 2025). "More recently SLFN11 immunohistochemistry of ovarian cancer tissue was able to predict response to platinum-based chemotherapies." (PMID 38001424, 2023). "Taken together, when assessing the available data about the immunohistochemical analysis of SLFN11 in tumor tissue, including ovarian cancer, the following important facts have to be pointed out." (PMID 35625957, 2022). "We also focus on the available data on the potential prognostic role of SLFN11 in ovarian cancer patients." (PMID 35625957, 2022). "Regarding the predictive role of SLFN11 in ovarian cancer, three studies have been published so far, two of them mainly exploratory in nature." (PMID 35625957, 2022). "Accordingly, in 2 other studies SLFN11 has been shown to be a biomarker of longer survival in CT-treated ovarian cancer patient cohorts." (PMID 34549724, 2021). "Overall, these results indicate an SLFN11 dependency of the immune modulation induced by cisplatin in ovarian cancer cell lines." (PMID 34549724, 2021). "We found that platinum treatments activated immune-related pathways in ovarian cancer cells in an SLFN11-dependent manner, representative of tumor-immune transactivation." (PMID 34549724, 2021). "We first selected 3 SLFN11-deficient (EFO-21, KURAMOCHI, RMGI, SLFN11–) and 3 SLFN11-proficient (OAW42, OV7 and OV-56, SLFN11+) ovarian cancer cell lines that were all STING pathway proficient, as illustrated by cGAS and IRF3 expression." (PMID 34549724, 2021). "We further show that SLFN11 mRNA level is a tumor biomarker predictive of overall survival (OS) and enhanced tumor response in breast, lung, and ovarian cancer patients treated with these chemotherapeutics." (PMID 31682620, 2019). "Analyses of multiple breast, lung, and ovarian cancer patient cohorts treated with chemotherapy confirmed SLFN11 mRNA expression as a predictive biomarker of longer overall survival and improved tumor response." (PMID 31682620, 2019).